BCL2L10 (BCL2 like 10)
Diseases named in the same sentence as BCL2L10 in open-access papers (continued):
Sharing a sentence is not in itself a finding about the gene and the disease.
mesothelioma (2 papers, 2021 to 2023). A usually malignant and aggressive neoplasm of the mesothelium which is often associated with exposure to asbestos. "All three proteins, UBQLN4, BCL2A1, and BCL2L10, were highly expressed in all cases of mesothelioma tissues." (PMID 34245648, 2021). "Our further study demonstrated that UBQLN4 acts as an anti‐apoptotic factor, which interacts with and stabilizes the anti‐apoptotic proteins BCL2A1 and BCL2L10, and regulates mesothelioma cell apoptosis in response to DNA damage." (PMID 34245648, 2021). "Immunohistochemistry assays indicated that BCL2A1 and BCL2L10 are highly expressed in mesothelioma." (PMID 34245648, 2021). "In this study, we not only identified UBQLN4 as a substrate for ATM, but also found that UBQLN4 interacts with and stabilizes the anti‐apoptotic proteins Bcl‐2‐related protein A1 (BCL2A1) and Bcl‐2‐like protein 10 (BCL2L10) and prevents mesothelioma cell apoptosis in response to DNA damage." (PMID 34245648, 2021). "Besides, we found that the depletion of BCL2A1 and BCL2L10 could enhance the sensitivity to the treatment of CPT in mesothelioma cells." (PMID 34245648, 2021). "Therefore, we further investigated the anti‐apoptotic mechanisms of BCL2A1 and BCL2L10 in mesothelioma and found that UBQLN4 could prevent MOMP in mesothelioma cells with CPT treatment." (PMID 34245648, 2021). "Phosphorylated UBQLN4 prevented cytochrome c release and inhibited apoptosis in mesothelioma during DNA damage by stabilizing BCL2A1 and BCL2L10." (PMID 34245648, 2021). "Our results thus not only revealed lots of potential candidates for ATM but also unveiled a mechanism that a new ATM substrate UBQLN4 regulates apoptosis in mesothelioma by stabilizing BCL2A1 and BCL2L10." (PMID 34245648, 2021). "Taken together, we uncover that about fifty potential substrates for ATM and clarify the mechanism that UBQLN4 inhibits the apoptosis in mesothelioma by phosphorylating the site of Ser318 and stabilizing BCL2A1 and BCL2L10." (PMID 34245648, 2021). "Furthermore, UBQLN4 inhibits the apoptosis in mesothelioma by stabilizing BCL2A1 and BCL2L10." (PMID 34245648, 2021).
Multiple Myeloma (2 papers, 2012 to 2024). "In addition, it has been recently reported that BCL2L10 expression was increased in patients with Multiple Myeloma (MM)." (PMID 22577154, 2012).
glaucoma (1 paper, 2022). Increased pressure in the eyeball due to obstruction of the outflow of aqueous humor. "In addition, we also quantitatively analyzed both groups for the expression of apoptosis-related (BAD, BAX, BCL2L10, and XIAP) and autophagy-associated (HAX1 and Beclin-1) marker proteins, since both signaling cascades are supposed to be highly involved in the molecular pathogenesis of glaucoma." (PMID 36313990, 2022).
glioma (1 paper, 2019). A benign or malignant brain and spinal cord tumor that arises from glial cells (astrocytes, oligodendrocytes, ependymal cells). "The BCL2L10 (BCL-B, Boo) is a negative regulator ofcell death in the human glioma cell." (PMID 31285648, 2019).
myeloid leukemia (1 paper, 2012). A clonal proliferation of myeloid cells and their precursors in the bone marrow, peripheral blood, and spleen. "Our results are in very good agreement with two studies in the literature that linked resistance of cancer cell lines established from solid tumor and myeloid leukemia to various chemotherapeutic agents and overexpression of BCL2L10 both at the mRNA and protein level." (PMID 22577154, 2012).
myeloid neoplasm (1 paper, 2012). Proliferation of myeloid cells originating from a primitive stem cell. "Moreover, in primary samples from patients they found that BCL2L10 promoter was methylated in approximatively one-half AML and related myeloid neoplasms, 13% of MDS samples and in none of the controls." (PMID 22577154, 2012).
ovarian carcinoma (1 paper, 2016). A malignant neoplasm originating from the surface ovarian epithelium. "As Bcl2l10 is highly expressed in the ovary, we can assume that the reduction of IRBIT expression in the ovarian cancer cell line leads to an increased activity of Bcl2l10, which may contribute to the usual resistance of cancer cells to apoptosis." (PMID 27995898, 2016).
Sepsis (1 paper, 2012). Sepsis is defined as life-threatening organ dysfunction caused by a dysregulated host response to infection. "In the subgroup of patients exhibiting low percentage of BCL2L10 positive cells, one patient died of sepsis, and all others patients remained AZA sensitive according to the IWG 2006 or AML2003 criteria." (PMID 22577154, 2012).
cancer (18 papers, 2011 to 2025). A tumor composed of atypical neoplastic, often pleomorphic cells that invade other tissues. "Ubiquitin-dependent proteasomal degradation has been foundto affect Bcl2L10 function as regulator of apoptosis, while increased expression ofBcl2L10 by gene amplification has been linked to acquired drugresistance in cancer cells." (PMID 36046354, 2022). "On thecontrary, overexpression of Bcl2L10 inhibited the growth ofhepatocellular carcinoma xenografts and reduced experimental lung metastasis." (PMID 36046354, 2022). "Despite a controversial role of BCLb/BCL2L10 in apoptotic-related functions, BCLb/BCL2L10 protein expression is inversely correlated with survival outcome of patients in various cancer types." (PMID 32549375, 2020). "This important discrepancy most likely reflects the inaccuracy of profiling BCL2L10 in cancer at the mRNA levels, as was remarked in recent publications." (PMID 33396645, 2020). "In contrast to these three main anti-apoptotic BCL2 proteins, the genes for the related anti-apoptotic BCL2 proteins Bfl1 (BCL2A1), BCL-w (BCL2L2) and BCL-B (BCL2L10) display little perturbation effects in cancer (mean Chronos Gene Dependency Scores −0.0454, −0.103 and 0.006, respectively)." (PMID 40113751, 2025). "Bcl-B/Bcl-2L10 is a multifaceted protein that exerts both pro- and antiapoptotic activities, allowing it to act as an oncogene as well as an oncosuppressor in different cancer types." (PMID 37899453, 2023). "We also investigated the dependency profile of BCL2 family proteins (BCL2, BCL2L10, BCL2A1, BCL2L1, and MCL1) in GBM within Cancer Cell Line Encyclopedia, and found that GBM cells show the greatest dependency on Bcl-xL (BCL2L1) for survival." (PMID 38383492, 2024). "Unlike our results, Bcl2L10 knockdown has been reported to promotethe proliferation of ovarian and gastric cancer cells." (PMID 36046354, 2022). "Therefore, low expression of BCLb/BCL2L10 in hepatic cell carcinoma (HCC) tissues and cells can release free BECN1 to regulate autophagosome formation and lead to cancer cell survival." (PMID 32549375, 2020). "In some cases, Bcl2L10 was evenreported not to affect apoptosis of cancer cells, thus indicating that in severalmodels it may not be a regulator of apoptosis." (PMID 36046354, 2022). "The reasons for these discrepancies in BCL2L10′s role in cancer have not been elucidated." (PMID 33396645, 2020).
tumor (11 papers, 2014 to 2025). "We next evaluated theinvolvement of Bcl2L10 in several steps during tumor progression, such as cellmigration, cell invasion, and VM." (PMID 36046354, 2022). "In many of these tumor types, the elevated BCL2L10 expression was correlated with poor prognosis." (PMID 33396645, 2020). "BCL2L10 was found to be overexpressed in several tumor types, but the mechanisms implicated in BCL2L10 expression have not been identified to date." (PMID 33396645, 2020). "Despite the fact that BCL2L10 was found to be overexpressed in several tumor types, the mechanisms underlying BCL2L10 overexpression have not been investigated." (PMID 33396645, 2020). "Moreover, we evidenced the ability of Bcl2L10 to promote the formation of VM, whichis a phenomenon indicating the de novo formation ofvasculogenic-like networks by aggressive tumor cells, and correlating with hightumor grade, short survival, invasion, and metastasis." (PMID 36046354, 2022). "Since we observed BCL2L10 transactivation by STAT3 in the model cell line HEK293, it is very likely that STAT3 drives BCL2L10 upregulation in other tumor types presenting constitutive activity of STAT3." (PMID 33396645, 2020). "In agreement with our in vitro results, wefound that in vivo tumor growth was not affected by Bcl2L10." (PMID 36046354, 2022). "Four genes (MYH1, PCDHB16, PCDHB15, and BCL2L10) showed a differential methylation profile between metastatic and primary tumour tissue samples (data not shown)." (PMID 36125262, 2022). "BCL2L10 staining was observed exclusively in the tumor tissue, whereas the immunoreactivity was not apparent in the adjacent noncancerous stroma." (PMID 33396645, 2020). "Following the literature, a tumor-promoting activity for the up-regulation of MCOLN2 and the down-regulation of FILIP1L and BCL2L10 can be hypothesized." (PMID 32911675, 2020). "The exclusion of genes like BCL2L10, OR10J6P, CDX2, and MT2P1 from the PPI network due to lack of interaction data may also warrant further investigation into their specific molecular functions or how their roles might be context-dependent within the tumor microenvironment." (PMID 39766765, 2024).
BCL2L10 also shares sentences with these, for which no sentence is quoted: leukemia (2 papers); myelodysplastic syndrome (2); acute leukemia (1); acute lymphoblastic leukemia (1); adenocarcinoma (1); breast neoplasm (1); cardiac arrhythmia (1); chronic myelomonocytic leukemia (1); colorectal cancer (1); infection (1); liver cancer (1); liver fibrosis (1); lung squamous cell cancer (1); squamous cell carcinoma (1); toxic epidermal necrolysis (1).